CLEC14A (C-type lectin domain containing 14A)
Diseases named in the same sentence as CLEC14A in open-access papers (continued):
Sharing a sentence is not in itself a finding about the gene and the disease.
tumor (continued). "CLEC14a (C-type lectin domain family 14 member) is a tumor endothelial cell marker protein that is known to play an important role in tumor angiogenesis, but the basic molecular mechanisms underlying this function have not yet been clearly elucidated." (PMID 28878328, 2017). "CLEC14a is exclusively expressed on tumor blood vessels in various cancers, including ovarian, liver, bladder, breast, kidney, pancreas, stomach, and esophageal cancer, but not on normal blood vessels." (PMID 28817103, 2017). "CLEC14A is a tumour endothelial marker upregulated in the vasculature of a range of different tumour types compared to healthy tissue." (PMID 26620208, 2016). "In this study, blocking MMRN2 interaction with ligands, namely CLEC14a, in vitro and in vivo, resulted in angiostatic effect and reduced tumor implant volume, implying that binding MMRN2 with its ligand results in natively proangiogenic signaling, an understanding that is currently debated." (PMID 38468017, 2024). "Furthermore, like CD248 and CLEC14a, anti-gal-1 vaccine has demonstrated promising anti-tumor effects in preclinical melanoma studies, citing enhanced cytotoxic T cell infiltration within tumors." (PMID 38468017, 2024). "Additionally, CAR-T targeting another endothelial marker, C-type lectin domain-containing 14A (CLEC14A), has been shown to reduce vascular density and diminish tumor burden." (PMID 36901858, 2023). "In the present study, the authors have observed that CLEC14A was significantly up-regulated in HCC tumors on both mRNA and protein levels; moreover, results of the clinical analysis showed the levels of CLEC14A in HCC patients were positively correlated with tumor size and differentiation." (PMID 35576868, 2022). "C-type lectin family 14, member A (CLEC14A), overexpressed in tumor endothelial cells, promoted sprouting angiogenesis via VEGF/VEGFR-2/VEGFR-3 pathway and vascular development and mediated cell–cell adhesion via its extracellular C-type lectin-like domain (CTLD)." (PMID 35784750, 2022). "Interestingly, the results of ROC analysis (AUC 0.8571 for tissue and 0.8145 for PBMCs) indicated that the expression of CLEC14A can distinguish the tumor tissue and the non-tumor adjacent tissue." (PMID 35576868, 2022). "Likewise, CLEC14A is an overexpressed tumor endothelial marker with relatively negligible physiological expression in normal endothelial cells." (PMID 36261831, 2022). "However, several C-type lectins, such as DC-SIGN, CLEC14A, macrophage galactose C-type lectin (MGL) contribute to tumor progression inducing immunosuppressive responses by sensing abnormal or altered tumor-associated carbohydrates." (PMID 35682991, 2022). "A previous study identified CLEC14A as a marker of tumor ECs." (PMID 34722263, 2021). "Thus, CLEC14A expression in vessels appears to be controlled by several factors and it is likely to be a combination of these that will determine which tumours and tissues show elevated levels." (PMID 32696621, 2020). "There was a significant inhibition of tumor growth in CAR-treated mice, and histological examination of tumor tissue demonstrated that there was also a significant reduction in the vasculature of CAR-treated tumors, with loss of CLEC14A-expressing vessels." (PMID 33004686, 2020). "CLEC14A expression can be induced under conditions of low shear stresses, such as occur in ill-formed vessels of tumor tissue, but other mechanisms may also contribute, including activin receptor–like kinase 1 signaling and hypoxia." (PMID 33004686, 2020). "Based on the meta‐analysis of CLEC14A transcripts, further protein expression studies are warranted for other non‐tumour pathologies to determine if protein expression levels could lead to unacceptable toxicity when targeting CLEC14A." (PMID 32696621, 2020). "However, immunohistochemical analysis of four healthy bladder tissue sections found that CLEC14A protein was only detected in a single case and at levels much lower than seen in some tumours." (PMID 32696621, 2020).
tumor (continued). "This may partly reflect the reduced flow rate often present within tumour vasculature; however, recent studies indicate that, in cancer, CLEC14A expression may be regulated by other pathways." (PMID 32696621, 2020). "Indeed, antibody blockade of CLEC14A interactions with its natural ligand, the endothelial‐specific extracellular matrix protein multimerin‐2, reduces angiogenesis and tumour growth in a mouse model." (PMID 32696621, 2020). "In tumours, however, high CLEC14A/TIE1 ratios indicate that CLEC14A mRNA levels are significantly higher in endothelial cells than could be expected based on shear stress alone." (PMID 32696621, 2020). "Prior to its suggested role in tumor angiogenesis, CLEC14A was described as an endothelial-specific adhesion molecule and further molecular characterization detected high levels of CLEC14A in the brain, retina, lungs, lymph nodes, ears, blood and lymphatic vessels of mice." (PMID 30132150, 2019). "Interestingly, the gene with the highest median co-expression coefficient in the set was CLEC14A, recently characterized as a tumor-specific endothelial marker." (PMID 30132150, 2019). "In future studies, we plan to plan to develop a human monoclonal antibody to HSP70-1A and further elucidate the detailed molecular mechanism that underlies the effects of the interaction between extracellular HSP70-1A and CLEC14a in tumor-bearing animal models." (PMID 28878328, 2017). "Together, these data suggest that CLEC14a is a novel therapeutic target for tumor angiogenesis, and that antibody-based targeting of CLEC14a may be an effective strategy for suppressing tumor angiogenesis." (PMID 28817103, 2017). "In the same paper, using the ectopic expression and siRNA-mediated knockdown of CLEC14a, the authors showed that CLEC14a regulates angiogenic functions including filopodia formation, endothelial cell migration, and tube formation, demonstrating the importance of CLEC14a in tumor angiogenesis." (PMID 28817103, 2017). "Collectively, this evidence suggests that CLEC14a may be a novel tumor endothelial cell-specific marker of tumor angiogenesis and a central regulator of tumor angiogenesis." (PMID 28817103, 2017). "However, we do not yet know the detailed molecular mechanism(s) through which CLEC14a acts in tumor angiogenesis." (PMID 28878328, 2017). "CLEC14A (EGFR5) plays a role in cell-cell adhesion and angiogenesis, because of its presence at higher levels in tumour endothelium it has been considered to be a candidate for tumour vascular targeting." (PMID 23526956, 2013). "Besides, tumor-associated glycoforms of conventional antigens, including SLAMF7, CLEC14A, PDPN, PODXL, and CD44, could also be ideal target antigens." (PMID 36261831, 2022). "In addition, CLEC14A was highly expressed in all the captured tumor EC types." (PMID 34722263, 2021). "Furthermore, recent clinical studies have demonstrated the remarkable potency of cytotoxic T‐cell‐based therapies targeting cancer antigens, and with this in mind we have developed T‐cells engineered with chimeric antigen receptors (CARs) that target CLEC14A on the tumour vasculature." (PMID 32696621, 2020). "However, the authors did not assess the efficacy of these antibodies in targeting this resistant cell line in tumour xenograft studies; therefore, the tangible benefit of CLEC14A targeting in tumour types resistant to VEGF blockade is yet to be fully established." (PMID 31287944, 2019). "Therefore, this study not only improves our understanding of the mechanism through which CLEC14a-CTLD regulates tumor angiogenesis, it also provides the possibility that the Fc fusion peptide may be useful for efficiently suppressing this process." (PMID 28878328, 2017). "Furthermore, their findings showed that the expression of CLEC14a is regulated by shear stress, suggesting that low shear stress at the tumor endothelial surface may be one of factors leading to CLEC14a expression on tumor vessels." (PMID 28817103, 2017).
tumor (continued). "Here, based on many increasing evidences, we hypothesize that the interaction between extracellular HSP70-1A and CLEC14a-CTLD may functionally stabilize CLEC14a expressed on the surface of tumor vessels and promote CLEC14a-mediated endothelial cell-cell contacts in tumor angiogenesis." (PMID 28878328, 2017). "Further, upregulation of selectins and CD93, CD248, and CLEC14a on tumor ECs prompt investigation as to whether group XIV CTLDs can serve as a mediator or master regulator of the activated EC phenotype in the face of tumor-derived signals as is described for E-selectin." (PMID 38468017, 2024). "The mechanisms by which CLEC14a mediates endothelial and ECM remodeling, within MMRN2 binding and beyond, seem to have serious implications for tumor microenvironment status." (PMID 38468017, 2024). "Like TM, CLEC14a expression is regulated by shear stress and interacts with HSP70-1A, both of which have potential implications for targeting tumor angiogenesis." (PMID 38468017, 2024). "CLEC14a, along with CD93, is recognized as part of a “common angiogenesis signature” characteristic of primary tumor tissue from head and neck squamous cell, breast, and clear cell carcinomas." (PMID 38468017, 2024). "CLEC14A was also a novel anti-angiogenic target for VEGF-dependent angiogenesis and tumor angiogenesis." (PMID 35967414, 2022). "The data indicate that even within the same tumour, tissue vascularity (as defined by PECAM1 expression) is highly variable as is CLEC14A expression." (PMID 32696621, 2020). "This tumor angiogenesis core gene signature also included CLEC14A and CD93, which together with endosialin and thrombomodulin constitute a C-type lectin family that are frequently up-regulated in tumor vessels." (PMID 31690961, 2020). "The C-type lectin domain containing group 14 family members CLEC14A and CD93 are proteins expressed by endothelium and are involved in tumor angiogenesis." (PMID 30847027, 2019). "Each family member has strong links to tumour development and in particular CD93, CLEC14A and CD248 have been proposed as attractive candidate targets for cancer therapy." (PMID 31287944, 2019). "This is the first study to propose use of an optimized antibody targeting CLEC14a‐CTLD, and the first study to demonstrate that CLEC14a‐CTLD is a novel anti‐angiogenic target for VEGF‐dependent angiogenesis and tumor angiogenesis." (PMID 29316206, 2018). "siRNA knockdown of CLEC14A or MMRN2 results in impaired angiogenesis in vitro, furthermore both of these proteins have been shown to be upregulated with tumour progression in spontaneous mouse models." (PMID 26620208, 2016). "Indeed, deletion of CLEC14A in mice results in elevated VEGFR2 signaling and increases tumor vessel leakage." (PMID 38441970, 2024). "The authors found that CLEC14A mRNA expression was dramatically increased in HCC tumor tissues in comparison with the adjacent non-tumorous tissues (p < 0.01)." (PMID 35576868, 2022). "Firstly, the expression of CLEC14A in HCC tumor tissue, as well as non-tumorous adjacent tissues, was examined and compared." (PMID 35576868, 2022). "Use of anti-CLEC14A CAR-T cells could be combined with CAR-T cells targeting another tumor endothelial marker, in order to increase tumor vessel targeting capacities." (PMID 35211124, 2022). "In addition, the type 14 family of C-type lectins have been considered promising targets for tumor treatment, including CD93, CLEC14A, and CD248." (PMID 35784750, 2022). "While a large percentage of tumours have elevated CLEC14A in their endothelium relative to healthy tissues, it is also clear from our analysis of both transcript and protein expression that not all tumours express CLEC14A." (PMID 32696621, 2020). "This means that CLEC14A targeted therapies would require confirmation of CLEC14A expression in the patient's tumour prior to therapy to avoid treating patients who would not respond." (PMID 32696621, 2020).
tumor (continued). "More recently, CLEC14A overexpression on the vasculature in ovarian cancer has been reported but did not correlate with survival in this tumour type 192." (PMID 31287944, 2019). "In this context, our 8-gene profile, as well as CLEC14A, might represent a starting point for the development of a companion tool for precision targeting of ALK1-driven tumor angiogenesis." (PMID 30132150, 2019). "Since it is well established that CLEC14A is expressed on vessels that experience low shear stress and aberrant blood flow, it is conceivable that only nonfunctional tumour vessels will be targeted by such agents." (PMID 31287944, 2019). "CLEC14a is also a tumor endothelial marker protein that localizes exclusively to tumor vessels, but not normal vessels." (PMID 29316206, 2018). "Our evidence also suggests that CLEC14a‐CTLD may be a novel potential anti‐angiogenic target for VEGF‐dependent angiogenesis and tumor angiogenesis." (PMID 29316206, 2018). "First, CLEC14a is a tumor endothelial marker protein that is exclusively expressed on tumor vessels, but not on normal vessels during tumor angiogenesis." (PMID 29316206, 2018). "A number of lines of evidence support the idea that CLEC14a‐CTLD may be a novel anti‐angiogenic target for VEGF‐dependent angiogenesis and tumor angiogenesis." (PMID 29316206, 2018). "Although increasing evidence supports the functional importance of CLEC14a in tumor angiogenesis, the related regulatory mechanism has not been intensively studied." (PMID 28878328, 2017). "While thrombomodulin, CD93 and CLEC14A are mainly expressed by endothelial cells, CD248 is expressed by vasculature-associated pericytes, activated stromal fibroblasts, mesenchymal stem cells and tumor cells, but not in the endothelium." (PMID 37443812, 2023). "However, the physiological relevance of CLEC14A expression in tumour cells themselves remains to be seen as such expression has not been reported in clinical specimens or in tumour cells by any other group." (PMID 31287944, 2019). "Our combined findings suggest that this improved antibody may effectively suppress abnormal VEGF‐dependent angiogenesis by CLEC14a‐positive tumor vessels without affecting VEGF signaling in CLEC14a‐negative normal endothelial cells." (PMID 29316206, 2018). "Interestingly although this elevated expression was indicated from transcript analysis using CLEC14A/PECAM1 ratios, it was not from CLEC14A/TIE1 ratios, implying that in this tumour elevated CLEC14A expression may be more a result of reduced flow rates." (PMID 32696621, 2020). "Therefore, to improve the efficacy of CLEC14A-specific CAR-based therapy for solid tumor vasculature, future studies could explore combining this approach with CARs targeting other TEMs to increase the proportion of tumor vessels that can be targeted." (PMID 33004686, 2020). "Unlike CD93 and CLEC14a but like CD248, expression of TM on tumor cells themselves seems to carry more relevancy to cancer biology than angiogenesis." (PMID 38468017, 2024). "CLEC14A expression in tumour tissues (normalised to PECAM1 or TIE1 expression) is also significantly above most, but not all, non‐tumour pathologies." (PMID 32696621, 2020). "Finally, as CLEC14A and CD93 have been described as proteins highly expressed in the tumour vasculature, with roles in angiogenesis, it remains to be investigated whether these molecules are also expressed and have roles in other routes in which a tumour can acquire a blood supply." (PMID 31287944, 2019). "Recent work detailing blockade with a CD93 mAb has led to interesting and promising results toward tumor vessel normalization rather than depletion as seen in antibody-directed binding to other group XIV CTLDs such as CD248 and CLEC14a as will be discussed in subsequent sections." (PMID 38468017, 2024).
cancer (15 papers, 2015 to 2026). A tumor composed of atypical neoplastic, often pleomorphic cells that invade other tissues. "CLEC14A is involved in regulating the growth of cancer cells, maintaining body hemostasis, and facilitating cell communication." (PMID 36900421, 2023). "The roles of CLEC14A in some types of cancers, for example, renal clear cell carcinoma lung adenocarcinoma, uterine carcinosarcoma, have been discussed previously." (PMID 35576868, 2022). "In recent years, CLEC family proteins were found to be up-regulated in several cancers, and the roles of CLEC14A as onco-genes have been investigated in different works, However, little was known about the function of CLEC14A in HCC." (PMID 35576868, 2022). "Here we report a comprehensive analysis of CLEC14A gene and protein expression in healthy, cancer and other diseased human tissues and also in informative healthy primate tissues." (PMID 32696621, 2020). "To evaluate the potential of CLEC14A as a target for safely treating solid tumours, we explored publicly available datasets to compare gene expression in healthy, cancer and other diseased human tissues." (PMID 32696621, 2020). "CLEC14A is a glycoprotein selectively overexpressed on the vasculature of many solid human cancers and is, therefore, of considerable interest as a target antigen." (PMID 33004686, 2020). "We conclude that CLEC14A is a promising target to enable development of novel anti‐cancer therapies for solid tumours." (PMID 32696621, 2020). "The gene with the highest median co-expression coefficient across all cancers is CLEC14A, which we infer to be a potential direct transcriptional target of ALK1 signaling through SMAD1/5." (PMID 30132150, 2019). "Elevated levels of CLEC14A transcripts were identified in some non‐cancer pathologies; such comorbidities may need to be excluded from trials of therapies targeting this marker." (PMID 32696621, 2020). "Interestingly, high expression of CLEC14A in this cancer type correlated with improved clinical outcomes." (PMID 31287944, 2019). "CLEC14a and EMCN were validated as TEC markers, extending their annotation in breast TEC, and ADM5 identified as a novel TEC marker in breast and other cancers." (PMID 41776551, 2026). "Other targets, including TNF receptor superfamily member 17 (TNFRSF17), CD22, CD38, CD33, and C-type lectin domain containing 14A (CLEC14A), demonstrated consistent but lower targeting potential across cancers." (PMID 39439803, 2024). "Four members compose the group XIV of CTLDcps: CD93, Clec14A, CD248, and Thrombomodulin, which have been studied extensively in human and mouse in the contexts of angiogenesis and cancer biology." (PMID 35659564, 2022). "Namely, CLEC14A, CD93, endoglin, and ANTXR1 (alias TEM8) have shown to be overexpressed in several cancers." (PMID 34770976, 2021). "Previously, we identified the glycoprotein CLEC14A as a TEM, highly expressed on the surface of vascular endothelial cells in many common human cancers but expressed at low or undetectable levels in healthy tissue." (PMID 33004686, 2020). "The group XIV of C-type lectin domain-containing proteins (CTLDcps) is one of the seventeen groups of CTLDcps discovered in mammals and composed by four members: CD93, Clec14A, CD248 and Thrombomodulin, which have shown to be important players in cancer and vascular biology." (PMID 35659564, 2022). "Given the widespread expression of CLEC14A in human solid tumors and the non-MHC restricted nature of CAR-expressing T cells, CLEC14A-specific CAR T cells could potentially treat a wide range of cancer patients." (PMID 33004686, 2020).
CLEC14A also shares sentences with these, for which no sentence is quoted: cervical cancer (1 paper); colon cancer (1); COVID-19 (1); emphysema (1); gastric cancer (1); head and neck squamous cell carcinoma (1); interstitial lung disease (1); kidney tumours (1); lung disease (1); melanoma (1); ovarian cancer (1); pulmonary fibrosis (1).